TLR9 (toll like receptor 9)
Diseases named in the same sentence as TLR9 in open-access papers (continued):
Sharing a sentence is not in itself a finding about the gene and the disease.
lupus (continued). "In particular, immune complexes containing the lupus autoantigen U1snRNP or nucleosomes activate DCs and autoreactive B-cells via TLR7 and TLR9, respectively, contributing in this way to pathogenesis of systemic lupus erythematosus." (PMID 23112799, 2012). "In this regard, different murine models of lupus have been used to examine the role of TLR9/7 in the response against self nucleic acids." (PMID 21423726, 2011). "In dendritic cells, TLR9 (and TLR7) activation induces among others high levels of type I IFN, a cytokine heavily implicated in the pathogenesis of Systemic Lupus Erythematosus and Sjögren's syndrome." (PMID 20490286, 2010). "This has led to the hypothesis that TLR9 might be implicated as risk factors in the development of autoimmune diseases such as systemic lupus erythematosus (SLE)." (PMID 19924287, 2009). "We inserted the chimeric TLRs into the endogenous locus of TLR7 and TLR9, respectively, in lupus-prone MRL/lpr mice and then studied signaling, TLR ligand-inducible gene expression, TLR localization, and, finally, the effect of the TIR domain swaps on lupus-like disease." (PMID 40794441, 2025). "The role of TLR7 in lupus is well recognized, but the role of TLR9 remains controversial." (PMID 40931063, 2025). "Recently, several mutations of the human Unc93b that enhance TLR7 but not TLR9 activity were shown to mediate a rare form of genetically mediated pediatric lupus." (PMID 40794441, 2025). "Disease exacerbation was abrogated when TLR7 was also deleted from TLR9 null mice, indicating that TLR9 could limit lupus pathogenesis by diminishing the deleterious effects of TLR7." (PMID 39000140, 2024). "However, although they exhibit similar tissue expression and are involved in similar signaling pathways, TLR7 and TLR9 have opposing inflammatory and regulatory roles in lupus-prone MRL/lpr mice." (PMID 36769633, 2023). "In any case, our findings imply that human PLD4 polymorphism and deficiency may have diverse phenotypic presentations ranging from hemophagocytic lymphohistiocytosis to lupus, and that all may be treatable by blockade of TLR9." (PMID 37555846, 2023). "Since we also know that TLR9’s negative regulation of lupus pathology requires its expression in B cells, this suggests that it may directly interact with TLR7 in some fashion, since TLR7’s role in driving disease is also B cell intrinsic." (PMID 37606042, 2023). "Thus, the roles and the relationship between TLR7 and TLR9 in lupus immune signaling have gradually received increasing attention and have been investigated." (PMID 36555668, 2022). "Conversely, TLR7 deletion completely suppressed lupus disease progression in TLR9−/− mice." (PMID 36555668, 2022). "Likewise, in a murine lupus model, CQ blocked TLR9-mediated proliferation of autoantigen-specific B-cells." (PMID 35211119, 2022). "Additionally, extracellular DNAs exacerbate lupus activity through type I IFN activation from DCs in the intestinal laminar propria through TLR-9." (PMID 35897790, 2022). "Furthermore, TLR9-deficient mice, excluding the role of TLR9 in the inhibition of TLR7-mediated responses, show high lupus activity compared to WT mice." (PMID 36359746, 2022). "We analysed sera from TLR7-, TLR9-, and TLR7/TLR9-double deficient lupus-prone MRL/lpr-mice." (PMID 34521462, 2021). "Notably, a recent study has shown that B cell-specific expression of TLR9, a sensor for bacterial DNA, is protective against lupus." (PMID 33240280, 2020). "Given that susceptibility to infections is one of the primary causes of morbidity and mortality in lupus patients, we evaluated splenic leukocytes to assess their ability to respond to viral and bacterial infections by using TLR7 and TLR9 agonists in vivo as a model of sterile inflammation." (PMID 32251357, 2020). "Similar regulatory role of TLR9 was demonstrated in pristane-induced murine lupus." (PMID 31354738, 2019).
lupus (continued). "TLR9 has been shown to regulate autoimmune responses in models of systemic lupus erythematosus; therefore, it is possible that TLR9 in particular may regulate the inflammatory response in the context of AD, promoting an environment that leads to tissue repair." (PMID 30953557, 2019). "In addition, in kidney biopsies from patients with lupus nephritis (LN), there was evidence of TLR3, TLR7, and TLR9 overexpression with a positive correlation between TLR9 expression and high activity, measured by renal-systemic lupus erythematosus (R-SLEDAI)." (PMID 30034390, 2018). "However, the studies performed so far have not been examined in the context of human SLE, either in the lupus-prone NZBxNZW or pristane-induced lupus models, to evaluate the role of circadian expression of TLR9 in autoimmunity." (PMID 30034390, 2018). "Because the levels of immune complexes in lupus sera are inversely correlated with CpG-induced IFN-α production in lupus PBMCs, pDCs activated in vivo, most likely through TLR9 stimulation with IC containing DNA, may become tolerant to further stimulation." (PMID 29052537, 2017). "Lupus-prone mice deficient in TLR9 do not develop anti-dsDNA autoantibodies, although other disease markers are increased." (PMID 28410407, 2017). "Thus, Tlr9 regulates lupus autoantibody production and disease in a spontaneous polygenic lupus model independent of the disease-accelerating effects of the Faslpr mutation." (PMID 28278279, 2017). "Genetic deficiency in TLR9 accelerates pathogenesis in the spontaneous polygenic MRL.Faslpr murine model of systemic lupus erythematosus, despite the absence of anti-nucleosome autoantibodies." (PMID 28278279, 2017). "Indeed, in the autoimmune disease systemic lupus erythematosus, TLR9 is an important molecular mediator of stimulation of the innate and adaptive immune responses that drive the autoimmune process." (PMID 28811679, 2017). "In murine lupus models, the role of TLR9 in the pathogenesis is unclear." (PMID 29052537, 2017). "It was recently shown that IVIg may modulate TLR9 expression and activation in pathological conditions such as systemic lupus erythematosus (SLE), suggesting a new additional mechanism of IVIg." (PMID 25886362, 2015). "Several studies have investigated the role of TLR9 signal in lupus-prone mice." (PMID 26068236, 2015). "Surprisingly, TLR9 deficiency in the lupus-prone mouse strain MRL/Mplpr/lpr did not reduce but increased disease severity." (PMID 25695778, 2015). "Systemic lupus erythematosus is an autoimmune disease in which recognition of endogenous ssRNA and dsDNA by TLR7 and TLR9 is an important pathogenic step for the induction of the IFN Signature and the production of autoantibodies against many self-antigens, including dsDNA." (PMID 24489947, 2014). "The capacity of B cells from lupus patients to produce cytokines upon TLR9 engagement becomes less efficient with increasing disease activity, suggesting that they either enter an exhausted state or become tolerant to TLR stimulation for cytokine production when disease worsens." (PMID 25385499, 2014). "Moreover, the reduction of cytokine production upon TLR9 stimulation was correlated with lupus activity and anti-ds-DNA antibody titers." (PMID 25385499, 2014). "In addition to Type I IFNs, splenic DCs produce various cytokines in response to TLR7/TLR9 stimulation by anti-chromatin immune complexes (IC), which are a driving factor of lupus pathology." (PMID 25093822, 2014). "TLR7 and TLR9 have been extensively studied using lupus-prone mouse models." (PMID 25538618, 2014). "Oligonucleotides that inhibit the response to TLR7 and TLR9 ameliorate disease in lupus-prone mice." (PMID 23772226, 2013). "Taken together, these studies suggest TLR9 may either protect or exacerbate autoimmune conditions depending on the genetic background of the lupus-prone mice." (PMID 22110541, 2012). "TLR-9 activation also regulates the production of anti-dsDNA antibodies in lupus-prone mice." (PMID 22761629, 2012).
lupus (continued). "TLR7 and TLR9 appear to have different roles in the development of murine lupus." (PMID 22110541, 2012). "Patients with active SLE have increased TLR9 expression in peripheral blood memory and plasma B lymphocytes, and TLR9 signaling controls anti-DNA autoantibody production from these B cells in murine and human lupus." (PMID 23140401, 2012). "In conclusion, prednisolone and TLR antagonist (hydroxychloroquine) may down-regulate expression levels of TLR7 and TLR9 in lupus patients, thereby decreasing the innate immune response to HPV infection." (PMID 22513098, 2012). "Moreover, B cells from SLE patients and healthy donors were almost equally competent to differentiate into antibody-secreting cells upon TLR engagement except for a reduction in the generation of IgG-secreting cells by TLR9-stimulated lupus B cells." (PMID 22952899, 2012). "In conclusion, prednisolone and TLR antagonist (hydroxychloroquine) may down-regulate protein levels of TLR7 and TLR9 in lupus patients, thereby decreasing the innate immune response against HPV infection." (PMID 22513098, 2012). "Alternatively, a series of recent analyses have revealed that pDCs also play a pathogenic role in autoimmune diseases such as systemic lupus erythematosus (SLE) and psoriasis by their dysregulated production of type I IFNs through engagement of endosomal TLR9 by self-DNA with autoantibody." (PMID 20470398, 2010). "In the current study, we characterized the role of the IFNAR2 chain of the type I IFN (IFN-I) receptor in the targeting of nucleic acid-associated autoantigens and in B-cell expression of the nucleic acid-sensing Toll-like receptors (TLRs), TLR7 and TLR9, in the pristane model of lupus." (PMID 19624844, 2009). "Refinement of the class R INH-ODN structure to combine optimal TLR7/TLR9 sequences in double-stranded carrier may result in a novel class of pathway-specific therapeutics for human lupus." (PMID 19476613, 2009). "This is highly relevant to the report by Marshak-Rothstein and colleagues who had shown that co-engagement of BCR and TLR-9 by complexes of anti-DNA antibody and DNA may provide a mechanism for stimulation of autoreactive B cells in lupus." (PMID 18625057, 2008). "In mouse models of SLE, B cell–intrinsic TLR9 expression is necessary for the generation of pathogenic autoantibodies against DNA, and in BALB/c mice specifically, TLR9 expression is required for lupus-like disease." (PMID 41178711, 2025). "The pathogenesis of systemic lupus erythematosus (SLE) is linked to the differential roles of toll-like receptors (TLRs), particularly TLR7, TLR8, and TLR9." (PMID 38791389, 2024). "TLR9 plays an important role in the development of some autoimmune diseases, which include systemic lupus erythematosus (SLE), autoimmune thyroiditis and autoimmune nephropathy." (PMID 38903498, 2024). "While the reasons that underly the sex-biased role of Tlr7 in pSD are unknown, studies in the lupus field demonstrate that Tlr9 plays a key role in regulating Tlr7-driven immune activation, as Tlr9−/− lupus mice show exacerbated disease that is ameliorated when Tlr7 is also deleted." (PMID 39310226, 2024). "Indeed, overexpression of B cell Tlr9 in a lupus model protected against lupus nephritis." (PMID 39310226, 2024). "Moreover, TLR9 deletion led to an exacerbation of lupus in mouse models." (PMID 37063843, 2023). "Thus, Pld4thss/thss represents a rare model in which mouse lupus etiology is TLR9 dependent." (PMID 37555846, 2023). "Inhibitory oligodeoxynucleotides (INH-ODN) can exert an immunomodulatory effect to specifically block TLR7 and TLR9 signaling in systemic lupus erythematosus (SLE)." (PMID 36555668, 2022). "Further investigation of TLR9 is needed since targeting TLR9 receptors and modulating TLR9 signaling have emerged as important strategies as it is involved in autoimmune diseases such as systemic lupus erythematosus (SLE)." (PMID 31022289, 2019).
lupus (continued). "Moreover, it has been proposed that TLR9 might be responsible for the initiation of autoimmunity, particularly in systemic lupus erythematosus (SLE), where the production of autoantibodies against double-stranded DNA (dsDNA) is a common characteristic." (PMID 30034390, 2018). "While the pathological role of TLR7 in human SLE and lupus nephritis in murine models is relatively accepted, the role of TLR9 remains controversial." (PMID 30210502, 2018). "TLR9 signaling may protect against lupus by modulating the activity of regulatory T cells." (PMID 29854762, 2018). "Considering the fact that pDC-IFN-α blockade therapeutics including anti-IFN-α antibody, anti-IFNAR, pDC inhibitors, and TLR9 antagonist are in clinical trials with promising results in lupus, controlling the pDC-IFN-α axis may also have a beneficial effect for the treatment of IgA nephropathy." (PMID 29403161, 2017). "In genetically lupus-predisposed background, high levels of IFN-α (known to be an important player in SLE pathogenesis) induce short-lived plasma cell differentiation and autoantibody production, which is further enhanced by co-stimulatory molecules, Toll-like receptor 9 (TLR9) engagement and BAFF." (PMID 31557984, 2016). "In the current study, the response of B cells from SLE patients and healthy donors upon TLR9 stimulation was analyzed in terms of proliferation and cytokine production and correlated with the lupus disease activity and anti-dsDNA titers." (PMID 25385499, 2014). "TLR7 and TLR9 recognition of self-RNA and self-DNA, respectively, contributes to autoimmune diseases such as systemic lupus erythematosus (SLE)." (PMID 23426999, 2013). "In systemic lupus erythematosus (SLE) ST2825 abolished production of autoantibodies in peripheral blood mononuclear cells from SLE patients stimulated with TLR9 agonist CpG which enables further human clinical testing." (PMID 23305364, 2012). "However, when Carabin-deficient mice are stimulated with a Toll-like Receptor 9 (TLR9) agonist (CpG-DNA), thereby mimicking a viral infection, we observe the production of anti-dsDNA antibodies and a lupus-like glomerulonephritis with immune deposits in a subgroup of mice." (PMID 23109291, 2012). "Since in AM14 B cells, INH-ODNs fail to inhibit signaling through the BCR, or by LPS, we concluded that the increased potency of Class R INH-ODNs for BCR/TLR9 coactivated autoreactive B cells could be advantageous for selective targeting of autoimmune B cells in lupus." (PMID 20490286, 2010). "However, the role of TLR9 in the pathogenesis of lupus in this strain of mice remains controversial as some reports suggest that TLR9 may be actually protective rather than pathogenic via induction of regulatory T cells." (PMID 20490286, 2010). "Systemic lupus erythematosus (SLE or lupus) and SjD are distinct diseases that are both characterized by heightened activation of TLR7 and TLR9 signaling networks that serve as potent modulators of chronic inflammation." (PMID 42112403, 2026). "Similarly, TRIM21, an autoantigen associated with Systemic Lupus Erythematosus (SLE), negatively regulates type I IFN production driven by TLR3, TLR7, and TLR9." (PMID 40495154, 2025). "In systemic lupus erythematosus (SLE, lupus), endosomal toll like receptors (TLRs), TLR7 and TLR9, that sense (self) RNA and DNA, respectively, by signaling via activation of MyD88, initiate the loss of self tolerance and control disease severity." (PMID 40794441, 2025). "Though challenging for many reasons, this direction is compelling, as it will open new therapeutic targets to specifically promote TLR9 protective signals and/or inhibit TLR7-TIR in lupus." (PMID 40794441, 2025). "However, TLR9 and TLR7 have been implicated in various autoimmune diseases such as systemic lupus erythematosus (SLE) and psoriasis, suggesting that endosomal TLRs can detect self-derived NAs as indicators of cellular stress and tissue damage." (PMID 40037613, 2025).
lupus (continued). "Probiotics like L. rhamnosus LC-STH-13 inhibit NF-κB activation by blocking TLR9 signaling and preventing IκBα degradation, thus reducing pro-inflammatory cytokines such as TNF-α, IL-6, and IL-1β in lupus-prone mice." (PMID 40534849, 2025). "However, overexpression of TLR9 does not cause lupus-like autoimmunity." (PMID 38169466, 2024). "Ultimately, these preclinical and clinical studies demonstrate that the role of the TLR9 and STING pathways in lupus pathogenesis is more complicated than two inflammatory cascades converging into a singular interferonopathy." (PMID 35693769, 2022). "We observed that TLR7 or TLR9 agonists induce higher amounts of MCP-1 and IL-6 on PMs from lupus-prone mice than control mice, confirming that PMs from diseased mice present a more pro-inflammatory phenotype." (PMID 35211864, 2022). "Carabin has also been reported to be a novel negative regulator of B-cell function in systemic lupus erythematosus (SLE) and B-cell lymphoma through inhibiting the crosstalk between BCR and TLR9 pathways." (PMID 35265067, 2022). "In this paper, when TLR7 or TLR9 was blocked alone, the IRS-661-nanoflower-treated group and the IRS-869-nanoflower-treated group showed better amelioration of lupus symptoms." (PMID 36555668, 2022). "Targeting TLR in SLE may be therapeutically advantageous based on the roles of TLR7 and TLR9 in the effector function of B cells in lupus-like disease and SLE patients as well as the distinctive characteristics of TLR signaling in B cells." (PMID 36439744, 2022). "We found that the NCF1 p.R90H variant facilitated endosomal cleavage and activation of TLR7 and TLR9 in the endosome, thereby boosting the TLR pathway and IFN-I production, which resulted in more serious autoimmune responses and aggravated lupus symptoms." (PMID 35788118, 2022). "The alleviation effect of inhibitory oligonucleotides of TLR9 has been confirmed, and TLR7 has also verified that it is one of the target molecules for lupus pathology." (PMID 36555668, 2022). "The generation of high-affinity autoantibodies and long-lived plasma cells in lupus is dependent on the development of a robust GC response, with TLR7 and TLR9 signaling in B cells likely being required for this response." (PMID 34197340, 2021). "The roles of TLR7 and TLR9 in B cells and their crosstalk with BCR ligation have been extensively studied in models for systemic lupus erythematosus (SLE)." (PMID 34293057, 2021). "NETs trigger a concerted activation of TLR9 and B-cell receptor (BCR) leading to autoantibodies production in lupus." (PMID 33959133, 2021). "TLR7 is known to play a pivotal role in autoantibody production in murine lupus and is localized within the intracellular endosome along with TLR3 and TLR9." (PMID 34884569, 2021). "Since lupus patients are prone to infections, groups of mice were injected with viral (Imiquimod, a TLR7 agonist) or bacterial (ODN 2395, a TLR9 agonist) surrogates." (PMID 32251357, 2020). "Ligand to TLR4 or a mixture of ligands to TLR7 and TLR9 were used, based on our prior experience demonstrating additive effect of TLR7 and 9 ligands in unmasking reversible anergy in NZB lupus." (PMID 31632407, 2019). "Defective central tolerance in lupus appears to be due to early interferon imprinting of immature B cells in the bone marrow that results in CD19 downregulation and impaired TLR9 responses." (PMID 31921145, 2019). "Recent studies on other autoimmune diseases, such systemic lupus erythematosus, have shown that microbial curli fibers can lead to the activation of TLR2 and TLR9 on DCs, thus stimulating immune responses, including increased type I IFN production." (PMID 31273267, 2019). "In systemic lupus erythematosus (SLE), the inhibitory effect of chloroquine (CQ) on TLR9 is limited." (PMID 30034390, 2018).